FN1 (fibronectin 1)
Diseases named in the same sentence as FN1 in open-access papers (continued):
Sharing a sentence is not in itself a finding about the gene and the disease.
triple-negative breast carcinoma (11 papers, 2020 to 2026). An invasive breast carcinoma which is negative for expression of estrogen receptor (ER), progesterone receptor (PR), and human epidermal growth factor receptor 2 (HER2). "Transcription of fibronectin 1, which is crucial for cell junction and migration of triple-negative breast cancer (TNBC) cells, was regulated by SIPA1 in a DBR-dependent manner both in vivo and in vitro." (PMID 37500797, 2023). "Elevated TGFB1-2 levels are correlated with increased aggression in triple-negative breast cancers; their inhibition also decreases the expression of VIM and FN1, genes found up-regulated in our model." (PMID 33922695, 2021). "Overexpression of DGKZ significantly reduced the expression of E-cadherin, while increasing the expression of N-cadherin and FN-1, and the cytoskeletal morphology of the cells had significant changes, indicating that DGKZ participated in the induction of EMT in triple-negative breast cancer cells." (PMID 35115500, 2022).
esophageal squamous cell carcinoma (10 papers, 2018 to 2025). Esophageal squamous cell carcinoma (ESCC) is a type of esophageal carcinoma (EC) that can affect any part of the esophagus, but is usually located in the upper or middle third. "FN1 overexpression is associated with poor survival in squamous cell carcinoma of the esophagus." (PMID 39769169, 2024). "The expression of fibronectin 1 (FN1) in esophageal squamous cell carcinoma (ESCC) remains controversial." (PMID 37026938, 2023). "In esophageal squamous cell carcinoma, a positive correlation between FN1 and LTBP1 has been demonstrated." (PMID 37947594, 2023). "For example, lnc-ABCA12-3 is a novel oncogene in esophageal squamous cell carcinoma (ESCC) competes with endogenous miR-200b-3p to regulate the expression of fibronectin 1 (FN1) in metastatic stages of the tumor." (PMID 33632341, 2021).
rheumatoid arthritis (10 papers, 2011 to 2025). A chronic, systemic autoimmune disorder characterized by inflammation in the synovial membranes and articular surfaces. "FN1 has been implicated in a variety of pathological processes, including cancer, infections, and rheumatoid arthritis." (PMID 36081567, 2022). "In the context of RA, overexpression of FN1 is linked to synovial membrane thickening and pannus formation, a critical feature of rheumatoid arthritis characterized by immune cell invasion and subsequent cartilage and bone degradation." (PMID 40176023, 2025). "CXCL12, C3, FN1, COL1A2, ACTB, VCAM1, and MMP2 were identified and finally verified as the hub genes, mainly enriched in pathways like leukocyte transendothelial migration, PI3K-Akt signaling pathway, viral myocarditis, rheumatoid arthritis, and platelet activation." (PMID 36398072, 2022).
Sepsis (10 papers, 2015 to 2026). Sepsis is defined as life-threatening organ dysfunction caused by a dysregulated host response to infection. "Peptides and/or phosphopeptides of common plasma proteins such as ITIH3, SAA2, SAA1, and FN1 showed increased observation frequency by Chi square (χ2 > 9, p < 0.003) and/or precursor intensity in sepsis." (PMID 32636717, 2020). "In agreement with the literature, peptides from ITIH3, SAA2, SAA1, and FN1 showed variation in observation frequency between ICU-Sepsis versus ICU Control." (PMID 32636717, 2020). "The FN1, ITIH3, SAA1 and other peptides observed were consistent with previous claims of utility for these proteins as sepsis biomarkers." (PMID 32636717, 2020).
endothelial dysfunction (9 papers, 2016 to 2025). In vascular diseases, endothelial dysfunction is a systemic pathological state of the endothelium (the inner lining of blood vessels) and can be broadly defined as an imbalance between vasodilating and vasoconstricting substances produced by (or acting on) the endothelium. "In contrast, the 2D hPSC-ECs and HMVEC-Cs upregulated genes associated with LECs and, alongside 3D hPSC-ECs, expressed genes implicated in endothelial dysfunction (KALRN, POSTN, FN1, respectively)." (PMID 38775849, 2024). "However, in DAHND, we also found decreases in VWF and FN1 gene expression, consistent with diminished angiogenic tissue properties and decreased endothelial dysfunction, respectively." (PMID 38565563, 2024). "Lastly, while we focused on AP1, FN1, and SPP1 in nicotine-induced endothelial dysfunction, the broader regulatory network—including their roles in cytoskeletal signaling, focal adhesion dynamics, and ECM–receptor interactions—remains unexplored." (PMID 40722963, 2025).
liver cancer (9 papers, 2010 to 2025). An epithelial or non-epithelial malignant neoplasm that arises from the liver. "The abnormal expression of FN1 has been proven to be associated with liver cancer." (PMID 38704528, 2024). "After identifying STAT3 and FN1 as hub genes for STA treatment of liver cancer, we performed single-gene analyses on these genes." (PMID 40772037, 2025). "Differential expression analysis of FN1 showed that FN1 was highly expressed in patients with liver cancer compared to normal individuals." (PMID 40223922, 2025). "FN1, a major component of the extracellular matrix, has also been implicated in the induction of EMT in liver cancer, contributing to enhanced motility and invasive behavior of tumor cells." (PMID 41002582, 2025). "By analyzing the common signaling pathways of STAT3 and FN1, their potential connection in liver cancer can be further revealed." (PMID 40772037, 2025). "Through in-depth studies of these pathways, a better understanding of the synergistic mechanisms of STAT3 and FN1 in liver cancer can be achieved, providing new targets and strategies for the treatment of liver cancer." (PMID 40772037, 2025). "After network pharmacology and single-gene analysis, we preliminarily identified STAT3 and FN1 as the molecular targets through which STA exerts its effect on liver cancer." (PMID 40772037, 2025). "Differential expression analysis of FN1 in patients with liver cancer and healthy individuals on the GEPIA 2 website showed that compared with normal people, FN1 expression was increased in patients with liver hepatocellular carcinoma (LIHC), p < 0.0001." (PMID 40223922, 2025). "The mutation analysis was used to assess genetic variation of liver cancer, and it was found that PDE4DIP mutations were the highest in almost all patients with liver cancer, followed by SYNE1, KMT2C, PKHD1 and FN1." (PMID 35602894, 2022). "Additionally, Sch B inhibited the migration of HCC cells in the co-culture system.The differentially expressed protein fibronectin 1(FN1) in liver cancer patients was higher than that in healthy people." (PMID 40223922, 2025). "In addition, in vivo experimental results also verified the conclusion that Sch B inhibits the growth of liver cancer by inhibiting the expression of FN1." (PMID 40223922, 2025). "Macrophage-derived FN1 promotes the migration of liver cancer cells via the JUN pathway." (PMID 40223922, 2025). "Although STAT3 and FN1 play different roles in liver cancer, there may be some connection between them." (PMID 40772037, 2025). "In TCGA liver cancer data, we found a positive correlation between the expression of FN1 and STAT3." (PMID 40772037, 2025). "For example, the PI3K-Akt and JAK-STAT signaling pathways may be key pathways in which STAT3 and FN1 are jointly involved, playing significant roles in the occurrence and development of liver cancer." (PMID 40772037, 2025). "Considering the high integration of HBV in the FN1 region, it can be inferred that the integration of the hepatitis B virus into the FN1 gene may influence protein expression, thereby promoting the development of liver cancer." (PMID 38704528, 2024). "Therefore, there is a certain association between FN1 and STAT3 in liver cancer." (PMID 40772037, 2025). "Moreover, after Mettl3 knockdown in liver cancer cells, Western blot analysis validated that Mettl3 knockdown decreased the protein level of Snail, MMP2, MMP9, and FN1, but increased that of E-Cad, in both HepG2 and MHCC97H cells." (PMID 32483411, 2020).
lymphoma (9 papers, 2007 to 2026). A malignant (clonal) proliferation of B- lymphocytes or T- lymphocytes which involves the lymph nodes, bone marrow and/or extranodal sites. "In accordance with its role in ECM formation, staining for FN1 localized to the fibrous strands in our lymphomas." (PMID 24499539, 2013). "This suggests that both the ECM component FN1 and the ECM remodelling SPARC can influence the survival of lymphoma cells and their interactions with the microenvironment." (PMID 24499539, 2013).
myocardial infarction (9 papers, 2016 to 2025). Gross necrosis of the myocardium, as a result of interruption of the blood supply to the area, as in coronary thrombosis. "For instance, Arg1 and Fn1 serve as markers of pro-fibrotic macrophages in murine myocardial infarction, where macrophages promote fibroblast activation by producing Arg1 and Fn1." (PMID 40953007, 2025). "Overall, the identified intercellular programmes aligned well with the existing literature on pro-fibrotic response upon myocardial infarction, including potential interactions of FN1 and SPP1 with ITGB1-containing complexes within ischaemic regions." (PMID 39223377, 2024). "For the I/R model of the heart is shown, that Fibronectin 1 is upregulated and its inhibition leads to a reduction of myocardial infarct size." (PMID 37751458, 2023). "Conversely, genetic ablation of Fn1 blunts the proliferation and survival of cardiac progenitor cells and attenuates vasculogenesis and cardiogenesis, leading to a continuous decline in cardiac function during recovery after 12 weeks of myocardial infarction." (PMID 35602095, 2022). "There are very few studies on Fn1 in acute myocardial infarction." (PMID 36435743, 2022). "Conversely, administration of Fn1 inhibitor RGDS to mice remarkably ameliorated I/R-induced myocardial infarct size, myocyte apoptosis, inflammation, oxidative stress, and fibrosis, which were associated with inhibition of AMP/ATP-LKB1-AMPK-dependent mechanisms." (PMID 35602095, 2022). "However, the effect of Fn1 on myocardial infarction and I/RI remains controversial." (PMID 35602095, 2022).
neuroblastoma (9 papers, 2016 to 2025). Neuroblastoma (NB) is the most common solid, extracranial childhood tumor. "Since expression of FN1 has been linked to the mesenchymal state of neuroblastoma, we analyzed the transcriptome of the human stem cell-derived ALK/MYCN tumors." (PMID 38451815, 2024). "Down-regulation of MYCN, ID2, TERT and FN1 has been also reported in neuroblastoma cells undergoing differentiation upon exposure to retinoids." (PMID 26893368, 2016). "Activated ALK promoted upregulation of FN1 and POSTN in our human stem cell model and in patients with amplified or mutant ALK neuroblastoma." (PMID 38451815, 2024). "Consistent with FN1 as a marker of mesenchymal neuroblastoma,2ALK/MYCN tumors were more mesenchymal than MYCN tumors, suggesting that ALK can bias neuroblastoma toward the mesenchymal cell state." (PMID 38451815, 2024).
brain tumor (8 papers, 2009 to 2025). "Moreover, the high expression of FN1 in the microenvironment can serve as an alternative therapeutic target for drug delivery involving brain tumors." (PMID 35954323, 2022).
endometrial cancer (8 papers, 2011 to 2025). Primary or metastatic malignant neoplasm involving the endometrium (mucous membrane that lines the endometrial cavity). "The in vitro study indicated that overexpression of SPARC in endometrial cancer cells and fibronectin 1 jointly activate fibroblasts, promoting cancer progression and invasion." (PMID 36982551, 2023). "It has been reported that the combination of miR-200c and FN1 can effectively inhibit the development of endometrial cancer in terms of FN1 expression in endometrial cancer cells." (PMID 34276798, 2021). "SPARC-expressing endometrial cancer cells activated fibroblasts only in the presence of FN1, which was abundantly secreted from the cancer cells." (PMID 33579227, 2021). "Thus, down regulation of FN1 is an additional mechanism by which miR-200c suppresses migration in aggressive breast and endometrial cancer cell lines." (PMID 21501518, 2011). "In a model of endometrial cancer, it was demonstrated that SPARC activates fibroblasts in the presence of FN1, which itself was secreted by SPARC-expressing endometrial cancer cells, leading to enhanced mobility and invasion." (PMID 41488007, 2025). "Since there is substantial evidence in the literature for FN1 and MSN being involved in cancer cell migration, we assayed the breast and endometrial cancer cell lines for expression of these proteins." (PMID 21501518, 2011). "Additionally, the four genes (FN1, DUSP4, LEF1, and SMAD9) identified can shed light on the mechanisms of recurrence in endometrial cancer." (PMID 34485158, 2021). "In other TNBC cells and type 2 endometrial cancer cells, either MSN or FN1 are expressed but not both." (PMID 21501518, 2011).
head and neck cancer (8 papers, 2014 to 2024). A primary or metastatic malignant neoplasm affecting the head and neck. "In order to comprehensively recognize the role and potential mechanism of the COL1A1, IL1A, MMP9, and FN1 genes in the prognosis of head and neck cancer, we constructed a miRNA-related regulatory network in the current study." (PMID 39065771, 2024). "FN1 was identified to be overexpressed in hepatocellular, gastrointestinal, head and neck cancers, which indicated its involvement in tumorigenesis." (PMID 24765172, 2014). "Gene expression database research demonstrated that FN1 could be used as a new marker of radiation resistance for head and neck cancer." (PMID 33193601, 2020).
leiomyoma (8 papers, 2017 to 2025). A well-circumscribed benign smooth muscle neoplasm characterized by the presence of spindle cells with cigar-shaped nuclei, interlacing fascicles, and a whorled pattern. "Several other genes, although upregulated in non-mutated samples, showed a greater magnitude of increase in expression in the mutated leiomyoma group, including FN1, DCX, and COL11A1." (PMID 36835153, 2023). "Several groups have reported that leiomyomas express higher levels of FN1 compared to myometrium." (PMID 36835153, 2023). "In agreement with the results of these studies, our results showed that 100 μM RSV significantly decreased the protein expression of COL1A1, α-SMA, and β-catenin, as well as the mRNA level of FN1 (fibronectin) in primary human leiomyoma cells compared to controls in vitro." (PMID 31013842, 2019). "In addition to activin A, TGF-β3 was reported to increase collagen1A1, fibronectin 1 and versican expression in both myometrial and leiomyoma cells." (PMID 28212568, 2017). "The involvement of many proteins such as FN1, COL1A1, BMP7, CCND1, EZH2, HMGA2, AhR, and E2F1 shown in the protein–protein interaction networks are well known in leiomyoma pathogenesis; others, such as SOX2, REN, PPARG, ABCB1, and NR3C1 are novel and require further investigation." (PMID 36835153, 2023).
pancreatic ductal adenocarcinoma (8 papers, 2015 to 2025). An infiltrating adenocarcinoma that arises from the epithelial cells of the pancreas. "Pancreatic ductal adenocarcinoma (PDAC) cells and CAF were both found to express FN1." (PMID 40226936, 2025).
pterygium (8 papers, 2009 to 2025). A wedge-shaped fibrovascular lesion arising from the bulbar conjunctiva and extending to the cornea. "FN1 encodes for fibronectin 1, which is a crucial glycoprotein in cell adhesion and migration during embryogenesis, wound healing and metastasis; and higher expression of FN1 has been observed in pterygium tissues." (PMID 32411530, 2020). "FN1 is also an important molecule involved in the pathogenesis of pterygium that induces pterygium cell adhesion and migration." (PMID 36398070, 2022). "It has been previously discovered that miR-200b-3p was downregulated in pterygium as a regulator of FN1." (PMID 36398070, 2022). "A previous study examined significant alterations in FN1 through DNA microarray analysis and reported that FN1 serves as a potential regulator of epithelial cell migration, extracellular matrix deposition and the epithelial-mesenchymal transition in pterygium." (PMID 32411530, 2020). "Principal component analysis in pterygium indicated a signature of matrix-related structural proteins, including fibronectin-1 (both splice-forms), collagen-1A2, keratin-12 and small proline rich protein-1." (PMID 19272163, 2009). "Genes up-regulated in pterygium include fibronectin (FN1), CEACAM5 (CEA), CD24, SPARC, MSMB and TFF1." (PMID 19272163, 2009). "Therefore, we speculated that hsa_circ_0002406 might promote the EMT process by sponging miR-1-3p/miR-26b-5p and then upregulating FN1 in pterygium epithelium." (PMID 36398070, 2022). "Interestingly, a recently published study demonstrated that silencing of SPARC inhibited the expression of profibrotic markers, such as alpha smooth muscle actin and FN1 in human pterygium fibroblasts and also mitigated their migration and contractile phenotype." (PMID 35174178, 2021). "Among those DE-mRNAs, matrix metallopeptidase 3(MMP-3), fibronectin 1 (FN1), tenascin C (TNC), LRRC15, KRT6A, COMP, AKR1B10, and MUC5AC were significantly upregulated, which was consistent with previous studies on pterygium." (PMID 36398070, 2022). "The expression levels of EMT markers, such as FN1 and VIM, were significantly higher in pterygium than those in normal conjunctiva." (PMID 33790949, 2021). "The expression of the five hub genes (ECM1, IQGAP2, FN1, GADD34, CXCL12) was determined by real-time PCR in comparisons between 10 normal conjunctival tissues and 10 pterygium tissues." (PMID 32411530, 2020). "Among the top 20 connective genes from PPI network, FN1, VWF, and IGFBP3 have been reported and expressed disorderly in pterygium." (PMID 31341891, 2019). "We found that hsa_circ_0002406 might upregulate FN1 and ADAM12 by sponging miR-26b-5p and miR-1-3p, respectively, thus promoting EMT in pterygium." (PMID 36398070, 2022). "We speculated that these highly expressed circRNAs may increase the expression of FN1, SDC2, and MEX3D by sponging miR-200b-3p and further promote pterygium formation and growth." (PMID 36398070, 2022). "MIR4435-2HG was co-expressed with FN1 and MMP2 and was highly expressed in pterygium." (PMID 33790949, 2021). "These experiments revealed a significant stromal immunoreactivity against FN1 in 4 out of 7 pterygia, which was absent in controls, as well as a slightly increased epithelial staining in one pterygium." (PMID 35174178, 2021). "FN1 was involved in cell adhesion and migration processes, which has been found to enhance the EMT in pterygium, and IGFBP3 could control cell proliferation." (PMID 31341891, 2019). "FN1 and the collagen family, including COL1A1, COL3A1, and COL4A1, were the components of ECM, involved in the fibrotic type of fibrosis and might be a group of significant genes in pterygium." (PMID 31341891, 2019). "Furthermore, through protein-protein interaction network and mRNA-lncRNA co-expression network analysis, key mRNAs including FN1, VCAM1, and MMP2, and key lncRNAs including MIR4435-2HG and LINC00968 were screened and might be involved in the pathogenesis of pterygium." (PMID 33790949, 2021).